SYT1 (synaptotagmin 1)
Diseases named in the same sentence as SYT1 in open-access papers (continued):
Sharing a sentence is not in itself a finding about the gene and the disease.
neurodevelopmental disorder (continued). "Since SYT1 Associated Neurodevelopmental Disorder was first described by the Baker and Gordon Lab in 2015, fifteen variants have been discovered." (PMID 36291375, 2022). "This study builds on the previous identification and characterization of SYT1-associated neurodevelopmental disorder to broaden the range of potentially pathogenic variants for clinical laboratory reporting." (PMID 35101335, 2022). "SYT1 associated neurodevelopmental disorder is a recently discovered disease with little known about the mechanism of action, the extent of the mutations within the SYT1 protein, and the severity of clinical manifestations." (PMID 36291375, 2022). "For the purposes of this review, we will be discussing the SYT isoforms of clinical and functional relevance related to SYT1-associated neurodevelopmental disorder." (PMID 36291375, 2022). "In the years since, multiple missense mutations have been implicated in what has been classified as SYT1 -associated neurodevelopmental disorder." (PMID 36291375, 2022). "The current paper expands on the genotypic and phenotypic spectrum of SYT1-associated neurodevelopmental disorder." (PMID 35101335, 2022). "Each of the missense mutations causing SYT1associated neurodevelopmental disorder have been implicated in the C2B domain of SYT1 thereby disrupting SYT1 function." (PMID 36291375, 2022). "We will highlight the genetic basis of SYT1-associated neurodevelopmental disorder along with known phenotypes, with possible interventions and direction of research." (PMID 36291375, 2022). "With expansion of the cohort, SYT1-associated neurodevelopmental disorder continues to demonstrate intersecting clinical features that are common among synaptic vesicle cycling disorders." (PMID 35101335, 2022). "Consistent with this idea, heterozygotic de novo mutations in the syt1 gene detected in patients have been shown to be associated with a neurodevelopmental disorder." (PMID 35193927, 2022). "We predict that the selective sweep occurring on the region around SYT1, mutations on which are associated with neurodevelopmental disorders, began 2,260 generations ago with a selection coefficient of s = 0.04 and an initial frequency of f = 0.02." (PMID 32853200, 2020). "Collectively, these data confirm that SYT1 mutation is associated with a recurrent neurodevelopmental disorder." (PMID 30107533, 2018). "Beyond prognostication, diagnosis of SYT1-associated neurodevelopmental disorder can have important treatment implications." (PMID 30107533, 2018). "The breakpoint disrupting SYT1 in the present case maps to Intron 9, abolishing the C2B domain, where most of the pathogenic missense variants linked to SYT1‐associated neurodevelopmental disorders are located, probably interfering with calcium‐binding properties." (PMID 41438914, 2025). "Recently, DNAH14 and SYT1 variants have been implicated in neurodevelopmental disorders." (PMID 38886689, 2024). "However, there has been no explanation thus far identifying the relationship between these other illnesses and SYT1-associated neurodevelopmental disorder." (PMID 36291375, 2022). "Increased availability of precise genetic testing has made it possible to effectively diagnose patients and may prove that SYT1 Associated Neurodevelopmental Disorder is more common than we had previously assumed." (PMID 36291375, 2022). "As for the functions of the selected hub genes, mutations in SYT1, the master switch responsible for allowing the human brain to release neurotransmitters, could lead to a rare neurodevelopmental disorder." (PMID 35627270, 2022). "Although allelic expressivity may not explain the whole pathophysiology of the SYT1-associated neurodevelopmental disorder, it could exacerbate synaptic manifestations of individual SYT1 variants." (PMID 35193927, 2022).
neurodevelopmental disorder (continued). "SYT1 protein level titration experiments not only revealed to us the distinct roles of SYT1 but may also could contribute to the understanding of the pathophysiological mechanisms underlying SYT1-associated neurodevelopmental disorders." (PMID 35193927, 2022). "It was reported in 2015 that eleven patients were diagnosed with SYT1-associated neurodevelopmental disorder, but it is likely that, with significant improvements and availability of clinical genetic testing, a significantly larger population of SYT1 mutations will be found." (PMID 36291375, 2022). "Additionally, we will highlight the genetic basis of SYT1-associated neurodevelopmental disorder along with possible interventions." (PMID 36291375, 2022). "Due to differences in the expression patterns of these proteins and the timing of their functions, mutations in synaptobrevin 2 and synaptotagmin 1 probably tend to cause neurodevelopmental disorders, while mutations in synaptobrevin 1 and synaptotagmin 2 tend to cause motor disorders." (PMID 35204679, 2022). "Integration of genetic, cellular, neural systems and cognitive investigations will enable a thorough understanding of SYT1-associated neurodevelopmental disorder with the prospect of precision medicine targeting each individual’s symptoms and underlying mechanisms." (PMID 35101335, 2022). "This study guides the diagnosis and molecular understanding of this rare neurodevelopmental disorder and highlights a key role for SYT1 function in emotional regulation, motor control, and emergent cognitive function." (PMID 35101335, 2022). "Data of impaired synaptic transmission in neurons expressing these mutations indicate that dominant‐negative effect is likely the molecular basis of SYT1‐associated neurodevelopmental disorder." (PMID 41438914, 2025). "Further studies are required to investigate the impact of exocytic rate and its manipulation on neural circuit activity in vitro and in vivo model organisms, to inform potential therapeutic strategies for individuals with SYT1-assosciated neurodevelopmental disorder." (PMID 30107533, 2018). "While several cell models for neurodevelopmental disorders display either shortened or elongated dendrites, dendritic abnormalities are absent in Syt1 KO neurons, and have not been associated with Syt1 disease mutations reported so far." (PMID 38321119, 2024).
tumor (15 papers, 2014 to 2025). "Univariate analysis using Cox regression revealed that several factors, including tumor status, distant metastasis, lymph node status, gender, age, and SYT1 expression, were significantly associated with the overall survival of CRC patients." (PMID 37958455, 2023). "We have not seen evidence of internalization of PS-targeting antibodies or betabodies by tumor cells, and, in fact, the bivalent Fc-Syt1 protein, analogous to betabodies, exhibited limited internalization compared to their tetravalent agent." (PMID 39159812, 2024). "Only DEFB1 was up-regulated in the tumor group; in contrast, SIAH2 and SYT1 were down-regulated in the low-risk group (Wilcoxon test, P > 0.05)." (PMID 38393698, 2024). "Subsequently, we verified the expression change of TSHR, KCNJ16 and SYT1 in 68 pairs of normal and tumor tissues." (PMID 37208644, 2023). "The expression of TSHR and KCNJ16 was lower in the tumor tissues than that in the paired normal tissues, whereas the expression of SYT1 was upregulated in the tumor tissues." (PMID 37208644, 2023). "Both in vitro and in vivo experiments demonstrated that SYT1 repressed CRC metastasis most likely by inhibiting tumor cell pseudopodial formation and migration." (PMID 37958455, 2023). "The mRNA expression level of SYT1 was higher in tumor tissues, while the expression of KCNJ16 was positively correlated with that of TSHR and was decreased in tumor tissues." (PMID 37208644, 2023). "Higher growth hormone levels (31.4 ± 6.7 ng/mL vs. 21.5 ± 7.2 ng/mL, p < 0.05), tumor size (11.9 ± 4.1 cm3 vs. 7.8 ± 3.5 cm3, p < 0.05), and tumor recurrence (22.6% vs. 12.9%) were seen in the high-SYT1 group compared to the low-SYT1 group." (PMID 31391849, 2019). "SYT1 overexpression also suppressed CRC metastasis in tumor-bearing nude mice in vivo." (PMID 37958455, 2023). "In addition, the surface of livers was rough and the elasticity was worse in the control mice compared with the SYT1-overexpressing mice, which suggest tumor metastasis to the liver." (PMID 37958455, 2023). "Because pseudopodial formation is an early sign of tumor cell movement, we speculated that SYT1 overexpression may inhibit CRC cell migration, invasion, and metastasis." (PMID 37958455, 2023). "A key finding of the present study was that SYT1 could suppress CRC metastasis by inhibiting the pseudopodial formation of tumor cells." (PMID 37958455, 2023). "In addition, Cox proportional hazards regression analysis was performed for 5-year overall survival rates, using each gene expression level (i.e., PFN2, PSEN1, and SYT1), tumor stage, pathological grade, and age as covariates." (PMID 35327465, 2022). "Interestingly, a 40-kDa form of SYT1 participates in the non-classical export of FGF1, a protein that regulates many cellular processes including angiogenesis, morphogenesis and tumor growth suggesting a potentially key role of SYT1 in cancer." (PMID 24505276, 2014). "Moreover, SYT1 overexpression promoted the dephosphorylation of ERK1/2 and downregulated the expressions of Slug and Vimentin, two proteins tightly associated with EMT in tumor metastasis." (PMID 37958455, 2023). "Interestingly, we found that SYT1 was downregulated both in CRC tissues and CRC cell lines, and overexpression of SYT1 could suppress CRC cell metastasis in tumor-bearing mice in vivo and migration in vitro." (PMID 37958455, 2023). "Taken together, the present study suggests that SYT1 may be a tumor suppressor in CRC." (PMID 37958455, 2023). "Consistently, SYT1 overexpression decreased the p-ERK1/2 protein levels both in the xenograft metastasis model and in the orthotopic transplantation tumor model." (PMID 37958455, 2023). "Compared with A375 cells, A375 xenograft tumor displayed an upregulation for glial and neuronal genes (GFAP, BDNF, MAP2, MTURN, ROBO2, SYT1 and TUBB3) and neural stemness genes (ASCL1, MSI1, PAX6, PDGFRA, SOX9, VIM, ZIC1/2)." (PMID 33468253, 2021).
tumor (continued). "Neuron functional genes such as CaMK2N1, MEG3, SNCB, SYT1, DKK3 are almost expressed in the marginal area of the tumor (not shown)." (PMID 39257581, 2024).
cancer (9 papers, 2010 to 2023). A tumor composed of atypical neoplastic, often pleomorphic cells that invade other tissues. "We identified five genes (KCNJ16, SLC26A4, TG, TPO, and SYT1) as potential cancer treatment targets." (PMID 37208644, 2023). "The results showed that the downregulation of ADCY9 and NMUR1 in LUAD can inhibit the growth and aggressiveness of cancer, while the upregulation of SYT1 had the contrary effects." (PMID 35627270, 2022). "In detail, SLC50A1 and SYT1 were significantly upregulated in all cancers compared to healthy bladder tissue." (PMID 36352089, 2022). "SYT1 confers proliferation advantages to cancer cells and promotes the survival of cancer stem cells." (PMID 34722255, 2021). "While the precise role of SYT1 in cancer is unclear, the presence of multiple chromosomal rearrangements within this gene suggests that this gene is prone to breakage." (PMID 24505276, 2014). "Emerging evidence shows that synaptotagmin 1 (SYT1) takes roles in a variety of cancers." (PMID 37958455, 2023). "Recent studies have shown that SYT1 is also involved in cancer regulation." (PMID 35627270, 2022). "SLC50A1 and SYT1 were significantly upregulated in all cancers compared to healthy bladder tissue." (PMID 36352089, 2022). "Consequently, mechanistic studies are needed to further elucidate the potential role of SYT1 and its chromosomal rearrangements in cancer." (PMID 24505276, 2014). "Taken together, we analyzed the Cancer Genome Atlas (TCGA) database and Gene Expression Omnibus (GEO) database, grouped by TSHR expression level, screened WDTC and ATC, finally identified two differentially expressed genes (DEGs), namely KCNJ16 and SYT1." (PMID 37208644, 2023). "SYT1 is a known gatekeeper of neurotransmitter release sensitive to calcium, that has been marked as a differentially expressed gene in GBM and other types of human cancers, and its expression is inversely correlated with the survival of patients with cancer." (PMID 35784465, 2022).
infection (7 papers, 2015 to 2026). The state of being infected such as from the introduction of a foreign agent such as serum, vaccine, antigenic substance or organism. "Since patients harbor one mutated and one WT allele, we co-expressed WT EGFP-SNAP25b with mutated EGFP-SNAP25b, by combining infection with separate viruses encoding WT and mutant protein in a 1:1 ratio, as done previously by others for Syt1." (PMID 38411501, 2024). "Loss of Syt1 and Syt7 results in enlarged MR1 vesicles and an increased number of MR1 vesicles in close proximity to Mtb-containing vacuoles during infection." (PMID 41979188, 2026). "Our results demonstrated a notable decrease in the levels of synaptotagmin-1 and synaptophysin post-infection." (PMID 39640294, 2024). "A. thaliana infection by powdery mildew fungi is also severely inhibited in syt1 mutant plants, but in this case the role of the plant E-Syt homolog SYT1 seems to involve endocytosis." (PMID 32793605, 2020). "Lentiviral-mediated infection of mouse primary neuronal cultures led to ~70 % reduction in Syt-1 expression levels as compared to the control." (PMID 26202512, 2015). "Along these lines, we observed that the serum levels of the EAE onset-leading NDICPs showed that the levels of GS and SYN2 remained relatively unaffected by adjuvants and infection, whereas ENO2 and SYT1 expression was more susceptible to modulation by these confounding factors." (PMID 28769926, 2017).
neurological disorders (7 papers, 2012 to 2026). "Overall, our data help in resolving some controversies in SYT1 functions in exocytosis and in our understanding of how SYT1 contributes to the pathophysiology underlying SYT1-related human neurologic disorders." (PMID 35193927, 2022). "Because monoallelic mutations in SYT1 lead to neurologic disorders, it raises the question of whether and which of the three SYT1 functions in NT release is impaired by reduced SYT1 protein amount." (PMID 35193927, 2022). "Beyond neurological disorders caused by SYT1 and SYT2 mutations, the remaining links to disease are still somewhat speculative and relatively understudied." (PMID 33619613, 2021). "Synaptotagmin-1 (SYT1), a potential target in treating nervous system disorders, regulates neuron exocytosis and the synaptic vesicle cycle." (PMID 36777638, 2023). "SYT1 not only participates in various biological processes, such as lipid transport and the pathophysiology of neurological diseases but also may play a crucial role in the pathogenesis and treatments of various tumors." (PMID 33718116, 2020).
movement disorder (4 papers, 2018 to 2025). Neurological conditions resulting in abnormal voluntary or involuntary movement, which may impact the speed, fluency, quality and ease of movement. "Future investigations will involve additional parent/carer-report questionnaires to further probe the neurological and behavioral domains impacted by SYT1 variants, such as visual behavior, movement disorder symptoms, repetitive behaviors, and hyperactivity." (PMID 35101335, 2022). "Accordingly, SYT1 is the major isoform mediating terminal dopamine release in the midbrain, providing a potential explanation for involuntary movement disorders." (PMID 30107533, 2018). "Hence the presence of an involuntary movement disorder may be suggestive of SYT1 mutation, but absence does not preclude this diagnosis." (PMID 30107533, 2018).
mental illness (3 papers, 2010 to 2023). "In the PPI network of these Egr targets in the DG region, the top key nodes tightly associated with distinct psychiatric disorders and addictive behaviors in previous studies included Syt1, Stx1a, Dlg4, Cplx1, Gria1, Snap25, Rab3a, and Bdnf81,86–91." (PMID 37758941, 2023). "Here, we show that Syt7 is a redundant Ca2+ sensor with Syt1/Doc2 to drive spontaneous glutamate release, which functions uniquely to activate the postsynaptic GluN2B-containing NMDARs that significantly contribute to mental illness." (PMID 34228711, 2021). "In addition, we considered the involvement of the genes in psychiatric diseases and we narrow down to MARCKS and SYT1." (PMID 20098743, 2010).
neurodegenerative disease (3 papers, 2021 to 2023). A disorder of the central nervous system characterized by gradual and progressive loss of neural tissue and neurologic function. "Given Syt1’s indispensable role in vesicle recycling, and recent studies that implicate Syt1 in neurodegenerative disease, this previously unknown interaction between DGKθ and Syt1 strengthens the notion that lipid-metabolizing enzymes are important regulators of neurotransmission." (PMID 35573662, 2022).
heart diseases (1 paper, 2025). "Synaptotagmin-1 (SYT1) is an important regulator of exocytosis and apoptosis and has been found expressed in the myocardium, while its functions in heart diseases have rarely been studied." (PMID 40279007, 2025).
SYT1 also shares sentences with these, for which no sentence is quoted: frontotemporal dementia (2 papers); maturity-onset diabetes (2); alcohol abuse (1); astrocytoma (1); autism spectrum disorder (1); autoimmune thyroid disease (1); benign infantile familial seizures (1); central nervous system disorder (1); cognitive (1); cyst (1); EEC syndrome (1); Ewing sarcoma (1); Gordon syndrome (1); liposarcoma (1); Motor delay (1); multiple sclerosis (1); myxoid liposarcoma (1); Neurodevelopmental delay (1); Nystagmus (1); Parkinson disease (1); primary immunodeficiency (1); prostate tumor (1); Retinal atrophy (1); rheumatoid arthritis (1); scoliosis (1); spinal muscular atrophy (1); Strabismus (1); triple-negative breast carcinoma (1); vascular dementia (1); viral infection (1).